GLI1 (GLI family zinc finger 1)
Diseases named in the same sentence as GLI1 in open-access papers (continued):
Sharing a sentence is not in itself a finding about the gene and the disease.
breast carcinoma (continued). "Microarray analysis of the invasive breast cancer tissue showed increased expression of GLI1 and forkhead box C2 (FOXC2), a transcription factor involved in embryonic development and tissue homeostasis." (PMID 26633513, 2015). "On the other hand Gli-1 expression was lower in the ER-positive breast cancer cell lines T47D and MCF7." (PMID 26389956, 2015). "We also treated breast cancer cells with the Shh ligand to examine the effect of Shh on Gli1 and Ptch1 mRNA expression." (PMID 24889938, 2014). "Reduced GLI1 expression impeded migration, clonogenicity, primary and secondary mammosphere formation and tumor formation by claudin-low breast cancer cells." (PMID 25252859, 2014). "The transcriptional similarities of induced EMT mammary cells to claudin-low breast cancer suggested the potential importance of GLI1 for this breast cancer subset." (PMID 25252859, 2014). "It will be interesting to determine if a similar phenomenon occurs in breast cancer, and if patients with tumors that co-express NFκB and GLI1 have a worse outcome." (PMID 25252859, 2014). "The ineffectiveness of cyclopamine on GLI1 expression is consistent with published results for breast cancer cell lines including SUM149, T47D, MCF7, and MDA.MB.231." (PMID 25252859, 2014). "We observed upregulation of GLI1 in mammospheres, and a decrease in primary and secondary sphere formation after GLI1 knockdown, strongly suggesting a role for GLI1 in maintenance of breast cancer stem cells/progenitor cells." (PMID 25252859, 2014). "This work highlights the importance of GLI1 in the maintenance of characteristics of metastatic breast cancer stem cells." (PMID 25252859, 2014). "It was shown that upregulation of ERα by E2 also upregulated Shh which canonically activated Hh-Gli signaling and Gli1 expression in human breast cancer cells." (PMID 25503972, 2014). "Our work supports earlier studies implicating GLI1 signaling in some breast cancer cell lines, albeit through different mechanisms." (PMID 25252859, 2014). "We have extended these findings to the claudin-low subtype as a class, and our findings lend evidence to the potential of GLI1 as a therapeutic target in breast cancer." (PMID 25252859, 2014). "It will be interesting to see if NFκB activity and GLI1 expression are correlated in mammary tumors." (PMID 25252859, 2014). "In one such study, it was observed that Gli1 expression correlated well with basal breast cancer subtype, and the patients with high nuclear expression of Gli1 had significantly reduced survival time." (PMID 23533807, 2013). "More definitive data to evaluate the role of GLI1 in tumour initiation and its relationship to NRP2 were obtained using a transgenic mouse model of breast cancer in which GLI1 is expressed under the regulation of the MMTV promoter." (PMID 23436775, 2013). "In another study that focused on triple negative breast cancers, it was observed that Smoothened and Gli1 were significantly upregulated in triple negative breast cancers, as compared to the other breast cancer subtypes." (PMID 23533807, 2013). "In breast cancer development there is little information on cilia involvement available, however, the cilia-associated genes Gli1 (Hh effector), RPGRIP1 (LCA) and DNAH9 (PCD) are commonly mutated in breast cancer." (PMID 23628112, 2013). "For instance, in breast cancer patients, a paracrine signature defined as high epithelial Hh ligand and high stromal Gli1 has been found to be an independent predictor for overall survival in multivariate analysis in a cohort of 279 patients." (PMID 23667589, 2013). "Both in vitro and in vivo genistein decreased breast cancer stem cells, and inhibited breast cancer stem-like cells through down-regulation of the Hedgehog-Gli1 Signaling Pathway." (PMID 24331293, 2013).
breast carcinoma (continued). "Using immunohistochemical analyses, we assessed the expression of the Hh ligand, IHH and the transcription factor GLI1 in a tissue array comprising 75 breast cancer tissues and 9 tissues representing normal breast." (PMID 22479615, 2012). "Specifically, expression of IHH, PTCH and GLI1/2 has been determined to be correlated with enhanced proliferation in invasive breast carcinoma, node metastasis and clinical stage of breast cancer." (PMID 22479615, 2012). "GLI1 is overexpressed in the majority of breast cancers and a role for GLI1 in breast cancer invasiveness has been reported." (PMID 21505458, 2011). "Sonic hedgehog contributes to a molecular signature segregating inflammatory breast cancers at different prognosis, whereas exposure to cyclopamine, an alkaloid blocking hedgehog pathway, suppresses Gli1 expression and breast cancer cell growth." (PMID 24212666, 2011). "GLI1 overexpression has clinical impact and in breast cancer correlates with poor patient prognosis." (PMID 21505458, 2011). "As our previous study indicated a crosstalk between the ERα and Hh pathways in ERα-positive breast cancer cells, we examined the expression of Hh-related molecules, including Shh, Ptched 1 (Ptc) and Gli1, in ERα-positive gastric cancer cells." (PMID 20087349, 2010). "Compared to the primary cell line HMEC (human mammary epithelial cells) and the immortalised benign cell line MCF12A, GLI1 expression was clearly upregulated in the analysed set of breast cancer cell lines." (PMID 19706168, 2009). "Additional studies validating these data and further analysing possible interactions of GLI1 with other Hh signalling members are underway to clarify the role of this important developmental pathway for the pathogenesis of human breast cancer." (PMID 19706168, 2009). "In the nucleus of normal breast tissues, GLI1 protein expression was less abundant (median IRS = 6) than in the nucleus of breast carcinoma cells (median IRS = 8) (P = 0.008, two-tailed Mann-Whitney U-test)." (PMID 19706168, 2009). "Considering the whole TMA 97% (198/204) of the analysed breast carcinomas and 76% (35/46) of all analysed normal breast tissues were shown to present abundant nuclear GLI1 protein expression." (PMID 19706168, 2009). "So far the discrepancies between these two studies remain unsolved and should therefore be topic of further analyses characterizing the potential of GLI1 as a new potential prognostic marker of human breast cancer." (PMID 19706168, 2009). "In conclusion, we showed nuclear GLI1 overexpression in human breast carcinomas relative to normal breast tissue on the RNA and protein level." (PMID 19706168, 2009). "Applying semiquantitative realtime PCR analysis and immunohistochemistry (IHC) GLI1 expression was analysed in human invasive breast carcinomas (n = 229) in comparison to normal human breast tissues (n = 58)." (PMID 19706168, 2009). "The highly significant correlation between SHH and GLI1 expression characterises GLI1 as a potential functional downstream target of the hedgehog signalling pathway in human breast cancer as well." (PMID 19706168, 2009). "Further studies will be conducted to validate overexpression of GLI1 in human breast tumours also on mRNA level and gain more insight into the relevance of Hh signalling for human breast cancer development." (PMID 19706168, 2009). "GLI1 expression was also studied on protein level using a larger cohort of human breast cancers (n = 204) as well as normal breast tissues (n = 46)." (PMID 19706168, 2009). "The aggressive behaviour of GLI1 positive breast cancers is supported by the finding that GLI1 overexpression is associated to unfavourable overall survival." (PMID 19706168, 2009). "Initial analysis of GLI1 mRNA expression in a small cohort of (n = 5) human matched normal and tumourous breast tissues showed first tendency towards GLI1 overexpression in human breast cancers." (PMID 19706168, 2009).
breast carcinoma (continued). "We were able to show significantly increased levels of nuclear GLI1 protein expression (median IRS = 8) in human breast carcinomas in comparison to normal breast tissues (median IRS = 6)." (PMID 19706168, 2009). "To assess the role of GLI1 for the progression of human breast cancer in more detail we next correlated GLI1 expression data to clinicopathological characteristics of the tumours." (PMID 19706168, 2009). "GLI1 mRNA was especially abundant in the cell line MDA-MB435s, which is a common in vitro and in vivo model for metastatic breast cancer behaviour stating a potential involvement of GLI1 signalling in human breast tumour metastasis." (PMID 19706168, 2009). "AF has been shown to suppress tumorsphere formation by regulating the Hedgehog/Gli1 signaling pathway in breast cancer stem cells, and also uniquely triggers ferroptosis through regulation of the AMPK/mTOR pathway, mechanisms which have not been characterized for HF." (PMID 41511301, 2025). "Our results indicate that this regulatory loop may be disrupted in GLI1-high breast cancer cells, leading to alterations in retinol metabolism and contributing to cancer progression." (PMID 39483334, 2024). "Through GLI1, which acts as a transcription factor, Hedgehog signaling leads to increased expression of CXCR4 receptors that are linked to enhanced metastatic properties and breast cancer cell survival." (PMID 38474826, 2024). "Furthermore, GLI1 knockout reduces the viability of breast cancer cells, and high expression of GLI1 in HR‐negative breast cancer is indicative of poor prognosis." (PMID 39558881, 2024). "The basal expression levels of GLI1/2 are higher in TNBC compared to HR‐positive breast cancer." (PMID 39558881, 2024). "Since SHH and GLI-1 are known to be prognostic markers in human breast cancer and GLI-1 is a critical transcriptional factor, we evaluated the expression of SHH and GLI-1 in normal dogs and dogs with MGT to investigate the relationship between the Hh signalling pathway and canine MGTs." (PMID 37932728, 2023). "Studies have indicated that GLI1 abnormally expresses in breast cancer, colorectal cancer, esophageal cancer and other malignant tumors, and can also regulate the activity of other transcription factors to stimulate the proliferation, differentiation, and transformation of tumor cell." (PMID 37198697, 2023). "In addition, a GLI1 isoform, called truncated GLI1, has also been reported to induce the activation of genes related to proliferation, migration, and angiogenesis of breast cancer." (PMID 36701089, 2023). "In this study, we compared the expression of GLI1 in normal and breast cancer tissues." (PMID 36046646, 2022). "High GLI1 expression has been observed in various breast cancer cell lines." (PMID 36046646, 2022). "Furthermore, the untreated tGLI1 brain metastases were significantly larger than untreated GLI1 metastases, confirming the previous results demonstrating tGLI1’s role in promoting the aggressiveness of breast cancer brain metastases." (PMID 36077791, 2022). "In addition to PTCH1, high SHH, SMO, GLI1, and GLI2 expression levels were all associated with a poor prognosis in breast cancer patients." (PMID 36142286, 2022). "GLI1 expression has also been analyzed in various breast cancer cell lines." (PMID 36046646, 2022). "Therefore, the components of the Shh-GLI1 signaling pathway are overexpressed in the human breast cancer cell line MDA-MB-231." (PMID 36046646, 2022). "Indeed, NFκB knockdown resulted in a significant decrease in GLI1 expression, and GLI1 knockdown resulted in decreased claudin-low breast cancer and EMT cell lines’ tumorigenicity." (PMID 34572373, 2021). "To evaluate whether ETV4 stimulate SHH signaling activation, we knocked down ETV4 expression and found decreased protein levels of SHH and GLI1 in ETV4-silenced breast cancer cells." (PMID 34052833, 2021). "Further, it elucidated the link between GLI1 expression and prognosis of breast cancer." (PMID 33494284, 2021).
breast carcinoma (continued). "Notably, high levels of Shh and GLI1 have been associated with the enhanced acquisition of CSC traits and chemoresistance in breast cancer, which can be attenuated with SMO inhibitors." (PMID 34572373, 2021). "Similarly, in the second dataset of 327 breast cancer patients, GLI1 overexpression was the only gene in the SHH pathway that showed significant associations with late stage (p = 0.047)." (PMID 34722544, 2021). "GLI proteins, especially GLI1, have demonstrated prognostic values for predicting survival among diverse cancer types, including breast cancer, liver cancer, pancreatic cancer, ovarian cancer, glioma, prostate cancer, colon/colorectal cancer gastric cancer, AML, and medulloblastoma." (PMID 34572373, 2021). "According to available TCGA data, GLI1 is related to YAP1 in breast cancer patients." (PMID 34445421, 2021). "Therefore, based on all the expression and statistical analyses in discovery cohorts, we further established the potential prognostic association of GLI1 and FGFR1 genes using normal and tumor pairs of 150 breast cancer patients." (PMID 34722544, 2021). "Additionally, GLI1 knockdown in claudin-low breast cancer cell lines significantly attenuated cell proliferation, migration, anchorage-independent growth, self-renewal, and reduced tumor xenograft growth in vivo." (PMID 34572373, 2021). "GLI1 knockdown in claudin-low cells reduced tumor growth of orthotopic xenografts, and treatment with nuclear factor κB (NF-κB) pathway inhibitor decreases GLI1 expression and protein levels in breast cancer." (PMID 33494284, 2021). "Similarly, Frost and colleagues found that Gli1 enhances breast cancer cell EMT and metastasis via up-regulation of MMP-11, suggesting that GLI proteins regulate numerous genes associated with EMT." (PMID 32391382, 2020). "In breast cancer, HH expression had no prognostic value while GLI1/2 and TGFB expression were associated with better survival, together with the mesenchymal/EMT and cell stemness metagenes." (PMID 32879407, 2020). "Breast cancer tissues exhibited an increase in Gli1 expressions." (PMID 32150666, 2020). "GLI1 knockdown in HR-negative breast cancer cells led to reduced viability in vitro." (PMID 32957513, 2020). "Interestingly, we found that Gli1 was significantly elevated at the mRNA level in breast cancer tissues compared with adjacent tissues." (PMID 32150666, 2020). "Importantly, co-expression of GLI1 and two GLI1 targets, EGFR and Snail, are associated with worse outcome in breast cancer patients, further underscoring the clinical relevance of this pathway." (PMID 32391382, 2020). "ER has previously been reported to enhance expression of GLI1 in breast cancer cells." (PMID 31036836, 2019). "Additionally, both SHH knockout and GANT61 inhibited translocation of GLI1 into nucleus providing the evidence for inactivation of GLI1 in breast cancer cells." (PMID 31036836, 2019). "Therefore, it was confirmed that abrogation of SHH/GLI1 axis have significant impact on regulation of EMT markers in breast cancer cells." (PMID 31036836, 2019). "TGF-β induces Gli1 and Gli2 in a Smad3-dependent manner in epithelial and mesenchymal cell lines, dermal fibroblasts, osteolytic Langerhans cells, breast carcinoma cells, and pancreatic ductal adenocarcinoma cells." (PMID 31297044, 2019). "Interestingly, evidence now shows that NF-κB subunit p65 can bind directly to the GLI1 promoter region, and inhibition of NF-κB decreased GLI1 activity in breast cancer cells." (PMID 30759860, 2019). "Moreover, aberrant transcriptional upregulation of GLI1 is seen downstream of NF-κB in claudin low breast cancer, a sub-type of TNBC." (PMID 31394751, 2019). "High GLI1 expression correlates with worse outcomes in breast cancer." (PMID 31394751, 2019). "Hedgehog signaling pathway molecule Gli-1 is important for migration and invasion of breast cancer." (PMID 29734730, 2018).
breast carcinoma (continued). "In addition, a GLI1 isoform called truncated GLI1 (tGLI1) has also been reported to induce the activation of genes related to proliferation, migration, and angiogenesis of breast cancer." (PMID 30423843, 2018). "Additionally, the cycloheximide (CHX) chase assay was used to assess MCF-7 breast cancer cell line for the effect of USP37 upregulation on endogenous Gli-1 protein." (PMID 30482232, 2018). "KCTD11 was reported to suppress the Hedgehog signaling pathway in medulloblastoma, and crosstalk between the Hedgehog and PI3K/AKT/mTORC1 pathways via Gli1 activation has been reported to occur in several types of cancer models including medulloblastoma, prostate cancer and breast cancer cell lines." (PMID 30142151, 2018). "Together, these data suggest endogenous USP37 may regulate Gli-1 protein stability in breast cancer." (PMID 30482232, 2018). "In addition, GLI1 over expressing breast cancer cell lines (MDA-MB-231 and MCF-7) were treated with GANT61 to explore its probable effects on metastasis." (PMID 29329585, 2018). "Moreover, osteopontin (OPN) regulates Gli-1 activity, expression and induces epithelial-mesenchymal plasticity in breast carcinoma." (PMID 29734730, 2018). "The Hh pathway is considered to control the self-renewal of CSCs in breast cancer; therefore, we tested the expression of representative Hh signaling factors (smoothened and Gli-1) and main stem cell markers (ALDH1 and OCT4) in USP37 knockdown cells and control cells by western blotting analysis." (PMID 30482232, 2018). "Our study was the first one to summarize researches of prognostic role of Gli1 in breast cancer." (PMID 29113369, 2017). "Moreover, both 3-year survival (HR = 1.74, 95% CI: [1.28, 2.36]) and 5-year survival (HR = 2.04, 95% CI: [1.62, 2.57]) were worse in high Gli1 expression breast cancer cohort compared with low Gli1 expression cohort." (PMID 29113369, 2017). "Therefore we carried out a meta-analysis based on available evidences in order to investigate Gli1 expression with survival and several clinic-pathological charactereristics in breast cancer patients." (PMID 29113369, 2017). "But the relationship between Gli1 over-expression and survival in breast cancer patients might be influenced by the clinic-pathological characteristics." (PMID 29113369, 2017). "In particular, TGF-β may induce GLI1 expression in a GLI2-dependent manner independently from SMO in breast cancer." (PMID 29456503, 2017). "Diao's study clarified that Gli1 would be a potential therapeutic target, moreover, could also act as a prognostic marker in breast cancer." (PMID 29113369, 2017). "Moreover, detection of Gli1 can provid more convincing evidences for guiding the diagnosis and treatment in breast cancer patients." (PMID 29113369, 2017). "In conclusion, over-expression of Gli1 tends to progressive stages and is related to unfavorable prognosis of breast cancer, which may become a potential prognosis indicator and therapy target in breast cancer." (PMID 29113369, 2017). "Moreover, the development of mammary tumors by the conditional expression of GLI1 in experimental mouse models further supports the implication of the Hh pathway in EMT-mediated breast tumorigenesis." (PMID 28974015, 2017). "Additionally, GLI1 knockdown enhanced the effect of tamoxifen in reducing the proliferation of four breast cancer cell lines." (PMID 27689403, 2016). "Blockade of Hh signaling pathway by Cyclopamine could significantly enhance NC-induced inhibition of Hh and Gli1 expression as well as inhibition of migration of breast cancer cells." (PMID 27313840, 2016). "This may partly explain the observation of a tamoxifen-induced increase in the proliferation of the ERα-positive ZR751 and BT474 breast cancer cells, which moreover, was accompanied by a sustained upregulation of GLI1 expression." (PMID 27689403, 2016). "Additionally, high GLI1 expression predicted worse distant metastasis-free survival in breast cancer patients." (PMID 27689403, 2016).